ZNF487 (zinc finger protein 487)
Description:
May be involved in transcriptional regulation.
Synonyms: KRBO1; ZNF487P
Gene: Protein-coding gene on chromosome 10 (43,436,830 to 43,483,181, forward strand). Ensembl gene ENSG00000243660.
Subcellular location: Nucleus
Subcellular location (Human Protein Atlas): Nuclear membrane; Cytosol; Nucleoplasm
Gene Ontology:
Molecular function: DNA-binding transcription factor activity, RNA polymerase II-specific; RNA polymerase II transcription regulatory region sequence-specific DNA binding
Biological process: regulation of transcription by RNA polymerase II; regulation of DNA-templated transcription
Cellular component: chromatin; nucleus
Homologues: Orthologues: chimpanzee ZNF487 (98% identical), macaque ZNF487 (88% identical). Paralogues in human: ZNF248 (33% identical), ZFP90 (31% identical), ZNF25 (29% identical), ZNF614 (29% identical), ZFP37 (28% identical), ZNF596 (28% identical), ZNF133 (28% identical), ZNF749 (28% identical), ZNF266 (27% identical), ZNF554 (27% identical), ZNF560 (27% identical), ZNF264 (27% identical), and 50 more.